PRR15L (proline rich 15 like)
Synonyms: ATAD4; MGC11242
Tractability: No criterion of Open Targets' tractability assessment is met for any kind of drug.
Gene: Protein-coding gene on chromosome 17 (47,950,851 to 47,960,483, reverse strand). Ensembl gene ENSG00000167183.
Subcellular location (Human Protein Atlas): Cytosol
Genetic constraint (gnomAD): Loss-of-function variants: 1 observed, 6.15 expected, observed/expected ratio (o/e) 0.16, 90% interval 0.057 to 0.77. That is too few expected variants to judge how well the gene tolerates losing a copy. Missense variants: 127 observed, 134.33 expected, observed/expected ratio (o/e) 0.95, 90% interval 0.82 to 1.1. Synonymous variants: 57 observed, 54.1 expected, observed/expected ratio (o/e) 1.05, 90% interval 0.85 to 1.31.
Homologues: Orthologues: chimpanzee PRR15L (100% identical), macaque PRR15L (99% identical), mouse Prr15l (84% identical), dog PRR15L (83% identical), pig PRR15L (83% identical), rat Prr15l (82% identical), guinea pig PRR15L (81% identical), rabbit PRR15L (79% identical), tropical clawed frog prr15l (51% identical). Paralogues in human: PRR15 (32% identical).
Diseases named in the same sentence as PRR15L in open-access papers:
PRR15L is named in the same sentence as 2 diseases in open-access papers, as found by Europe PMC text mining. Sharing a sentence is not in itself a finding about the gene and the disease. The quoted sentences say what the papers report.
prostate carcinoma (1 paper, 2014). A carcinoma that arises from epithelial cells of the prostate gland. "We then selected six genes (HNRNPH1, DSC2, FBXO9, MANEA, OR51E1, PRR15L) for validation by qRT-PCR that were over-expressed in prostate cancer across all datasets and showed high fold changes in our microarray." (PMID 25003216, 2014).
PRR15L also shares sentences with these, for which no sentence is quoted: cancer (3 papers).